INS (insulin)
Diseases named in the same sentence as INS in open-access papers (continued):
Sharing a sentence is not in itself a finding about the gene and the disease.
Insulin resistance (continued). "Second, given that Rnf13 gene disruption in hepatocytes exhibits significant impacts on insulin resistance and blood glucose, whether RNF13 participates in the regulation of insulin signaling pathways in other metabolic organs merits further investigation." (PMID 37857628, 2023). "Fasting glucose and insulin levels were not elevated; however, insulin resistance as measured by HOMA was increased (3.53 ± 3.61 vs 1.84 ± 0.75, P = 0.047)." (PMID 37253232, 2023). "The exact mechanisms leading to this rapid development of brain insulin resistance remain incompletely understood, but likely involves the increased expression of negative feedback inhibitors of the insulin-signaling cascade are likely involved." (PMID 37100238, 2023). "Total cholesterol (AUC = 0.626, p = 0.013), LDL cholesterol (AUC = 0.670, p = 0.001), and TC/HDL (AUC = 0.620, p = 0.019) significantly classified subjects as insulin-resistant, with LDL cholesterol showing the highest AUC for the classification of insulin resistance." (PMID 37274075, 2023). "In addition, we found that 6-gingerol significantly decreased fasting serum glucose and insulin levels in HFD-fed mice, as well as homeostatic model assessment for insulin resistance (HOMA-IR)." (PMID 37047258, 2023). "Female Irs1KO mice, which had reduced glucose tolerance and insulin sensitivity, were longer-lived than control animals, suggesting that insulin resistance does not necessarily limit survival." (PMID 36812323, 2023). "Independent of the cut-off, youths with high levels of G60 showed higher levels of G120, insulin resistance (IR), triglycerides to HDL ratio (TG/HDL), alanine aminotransferase (ALT), and lower insulin sensitivity (IS) and DI than youths with lower levels of G60." (PMID 37297565, 2023). "Another stream of evidence also suggests that insulin resistance is not driver of early metabolic defects in TS, in that fasting glucose and insulin levels in euglycemic individuals with TS are similar or even lower than in controls." (PMID 36875465, 2023). "Additionally, homeostatic model assessment of insulin resistance (HOMA-IR), which is derived from fasting plasma glucose and fasting insulin, has been used as an alternative indictor for defining IR." (PMID 37065738, 2023). "An inverse relationship between glycated haemoglobin, insulin level, and insulin resistance with the trabecular bone score was reported in non-diabetic postmenopausal women." (PMID 37569816, 2023). "In studies using a rodent model of diet-induced obesity and insulin resistance, we found that an ethanolic extract from A. dracunculus (termed PMI5011) lowers blood glucose and improves insulin levels comparable to troglitazone (a TZD) by enhancing insulin action in skeletal muscle." (PMID 37686232, 2023). "One mode is ‘defective phosphorylation’, whereby insulin increases or decreases the abundance of a phosphosite in control cells but fails to do so in insulin resistance." (PMID 36808134, 2023). "In a 2020 meta-analysis evaluating whether low-calorie diets improved insulin sensitivity in women with PCOS, a greater reduction in insulin resistance (IR) was reported when a low-carbohydrate diet was prescribed rather than a high-carbohydrate diet." (PMID 37630772, 2023). "TNFα negatively affects insulin signaling by attenuating the insulin-stimulated tyrosine phosphorylation of the insulin receptor and insulin receptor substrate 1 (IRS1) in the WAT and muscles, leading to insulin resistance." (PMID 37755259, 2023). "Vitamin D deficiency increased the levels of fasting blood sugar, fasting serum insulin, and homeostasis model assessment (HOMA) of insulin resistance and decreased the secretion of HOMA of β-cell function, which led to insulin resistance and glucose metabolism disorder." (PMID 36178657, 2023).
Insulin resistance (continued). "Additional evidence suggesting that insulin resistance is not the primary driver of hyperglycemia is highlighted in three studies comparing IVGTT-derived measures of insulin sensitivity in individuals with TS to controls." (PMID 36875465, 2023). "In a study examining the molecular basis of insulin resistance, researchers identified a small molecule, Co-Insulin, which binds specifically to insulin rather than to the insulin receptor (IR)." (PMID 38138975, 2023). "Serum 1H-NMRS metabolomics profiling indicated sexual dimorphism in the responses to oral macronutrient challenges, which were apparently driven by the central role of postprandial insulin effects with obesity, and to a lesser extent PCOS, exerting modifying roles derived from insulin resistance." (PMID 37736753, 2023). "As inositols play role in various steps of insulin signaling pathway, they can improve insulin resistance regardless of its origin." (PMID 37836508, 2023). "The authors of this study also observed the positive correlations between LCN2 and features of insulin resistance: fasting plasma glucose (FGP), HOMA-IR, fasting plasma insulin (FPI), high-sensitivity C-reactive protein (hs-CRP), total cholesterol and triglyceride." (PMID 38203346, 2023). "Our data show that numerous plasma protein N-glycans associate with markers of metabolic status, such as fasting glucose and insulin levels, markers of insulin resistance and lipids, even though we observed no hepatic dysfunction in our subjects." (PMID 37079606, 2023). "A high prevalence of insulin resistance was identified in a sample of 154 non-diabetic PD patients, with 58% being insulin-resistant as indicated by abnormal Homeostatic Model Assessment for Insulin Resistance (HOMA-IR) scores." (PMID 36258018, 2023). "None of these mechanisms showed a response to insulin stimulation indicating severe insulin resistance." (PMID 36967414, 2023). "Using this approach, we identified 9 loci not previously associated with post-challenge insulin resistance in studies of European ancestry, including SLC2A4, which encodes the glucose transporter implicated in insulin-stimulated glucose disposal." (PMID 37291194, 2023). "Here, we provide intriguing data that urobilin levels are positively associated with adiposity and BMI in obese men and women and also with insulin resistance in women, which was determined using the Homeostatic Model Assessment for Insulin Resistance (HOMA IR), a measurement of insulin sensitivity." (PMID 36671031, 2023). "It is worth mentioning that a meta-analysis of nine RCTs found that compared with traditional yogurt, probiotic yogurt did not significantly improve fasting blood glucose, fasting insulin, insulin resistance, and other indicators of T2DM/obesity in patients." (PMID 36688679, 2023). "In contrast, studies conducted among participants with insulin resistance did not confirm a positive influence on insulin sensitivity and endothelial function; however, the inflammatory state was reduced." (PMID 36986170, 2023). "On the other hand, T2DM develops as a result of a relative lack of insulin due to insulin resistance." (PMID 38116309, 2023). "In the state of insulin resistance, insulin does not entirely suppress the activity of HSL in adipose tissue, leading to enhanced lipolysis and the release of fatty acids." (PMID 36677026, 2023). "T2D develops when early-phase insulin secretion can no longer overcome insulin resistance, and postprandial hyperglycemia occurs." (PMID 37049602, 2023). "When the Δchanges were examined, the fact that fasting insulin decreased by 35.90%, c‐peptide by 19.49%, and HOMA‐IR by 41.07% in DCm and was approximately two times higher than D indicates that CM is effective in insulin resistance‐related parameters." (PMID 38107130, 2023).
Insulin resistance (continued). "In the low CEC group, insulin signaling was disrupted, with increased glucose (p = 0.02) elevated insulin levels and a higher homeostatic model for insulin resistance (HOMA-IR; both p < 0.001) suggesting insulin resistance in the poor CEC group." (PMID 36891247, 2023). "The HOMA-IR index, which has been widely employed to detect the function of β-cell and insulin resistance, is also limited in patients who have received insulin therapy or without functioning β-cells." (PMID 37312120, 2023). "In terms of other biochemical variables, the case group showed elevated levels of FPG, insulin, and the HOMA-IR index, indicating increased insulin resistance compared to the normal group, which suggests potential metabolic dysregulation in individuals with obesity." (PMID 37862340, 2023). "From early studies, it has become evident that the latter is not only a consequence insulin resistance, as the degree of hyperglycemia does not fully account for the the augmented secretion of insulin." (PMID 36882643, 2023). "After 24 weeks, homeostatic model assessment of insulin resistance (HOMA-IR) (16.54 ± 7.81 vs. 29.09 ± 36.56, P = 0.027) and fasting serum insulin (FSI) (6.86 ± 3.45 vs. 11.13 ± 12.66 μU/ml, P = 0.032) were significantly lower in the vitamin K group compared to placebo." (PMID 37552330, 2023). "Thus, less time-consuming and simpler approaches, such as the quantitative insulin sensitivity check index (QUICKI), or its reciprocal, the QUICKI-IR, as well as the homeostatic model assessment of insulin resistance (HOMA-IR), have been developed." (PMID 36677025, 2023). "The main clinical feature of MetS is insulin resistance but measuring circulating insulin is not routine in clinical practice." (PMID 37375611, 2023). "An absence of estrogen can similarly generate insulin resistance, impaired insulin function and beta cell apoptosis." (PMID 37755297, 2023). "Accordingly, it has been shown that melatonin alleviates cognitive impairments by reducing brain insulin resistance in elderly rats on a HFD and that intranasal insulin administration improves memory and other cognitive functions in healthy adults with obesity." (PMID 36671568, 2023). "However, insulin resistance is proposed to be induced by mitochondrial ROS generation and parallel inhibition of the phosphatidylinositol 3-kinase (PI3K)/AKT insulin signaling pathway." (PMID 36670985, 2023). "A meta-analysis of the effects of tree nuts on glycemic indexes showed that tree nut consumption yields a modest reduction in fasting insulin levels and insulin resistance (based on HOMA-IR score), but does not change fasting glucose levels." (PMID 38140310, 2023). "Fasting plasma glucose and glycated haemoglobin (HbA1c) concentrations were lower whereas the homeostatic model assessment of insulin resistance (HOMA-IR), 2-h post-load glucose and fasting insulin concentrations were higher in pregnancy as compared to both preconception and postpartum." (PMID 36782297, 2023). "Type 2 diabetes (T2D) occurs when the body does not produce enough insulin, or when the cells cannot use insulin properly, a state known as insulin resistance." (PMID 36774491, 2023). "The AT insulin resistance index (ATIR) is another marker of adipose tissue quality that reflects the metabolic dysregulation of lipolysis and can be easily estimated by the serum levels of insulin multiplied by free fatty acids (FFAs)." (PMID 37391843, 2023). "Since our predominant metabolic phenotype was glucose intolerance due to impaired insulin secretion rather than insulin resistance, we further investigated the role of beta-cell dysfunction upon gavage with particulate air pollutants." (PMID 36895000, 2023). "Hence these results suggest that insufficient signaling through the MAPK pathway, as is observed in obesity, plays a role in the development of brain insulin resistance and is particularly important in the regulation of WAT insulin action." (PMID 37100238, 2023).
Insulin resistance (continued). "At the glucose homeostasis level, SOF induced a significant hypoglycemic effect in the exposed female rats, with no significant changes in the serum insulin level or the insulin resistance index (HOMA-IR)." (PMID 37958828, 2023). "We wanted to verify CNS insulin resistance, via CNS insulin receptor blockade using S961, did not affect distribution of 125I-insulin following IN delivery." (PMID 37076875, 2023). "The TyG index, as an ideal surrogate of insulin resistance regardless of insulin treatment status, has been widely validated to be robustly related to cardiovascular events." (PMID 36890516, 2023). "Metformin, which increases cell sensitivity to insulin, is without doubt, a reasonable pharmacological strategy for treating diseases whose pathophysiology is characterized by insulin resistance." (PMID 37765126, 2023). "Insulin resistance is a state in which the cells of the body do not exhibit their usual sensitivity to insulin and, as a result, do not uptake glucose from the blood as efficiently as they would otherwise." (PMID 37899888, 2023). "Third, some serum markers including serum insulin and leptin level, hepatic and peripheral insulin resistance, were not measured in the current study." (PMID 36658285, 2023). "In conclusion, human genetic data coupled with in vivo and in vitro experiments clearly indicate a critical role of BRSK2 in regulating GSIS function, subsequent systematic insulin resistance, and T2DM through crosstalk between β cells and insulin target tissues." (PMID 37188647, 2023). "Plasma leptin levels had a positive correlation with some clinical parameters of MetS, including obesity (BMI and WHR), HbA1c levels, and insulin resistance (insulin level, HOMA-IR index) but were not related to hypertension, hyperglycemia, and dyslipidemia." (PMID 37703108, 2023). "Another mode of dysregulation we considered is ‘emergent phosphorylation’, whereby a phosphosite is not altered by insulin in control conditions but becomes regulated by insulin only in insulin resistance." (PMID 36808134, 2023). "It therefore is not surprising that “insulin resistance” does not mean full suppression of hormonal activity but only downregulation of some insulin functions such as induction of glucose transporter translocation to the cell membrane." (PMID 37854186, 2023). "The HOMA-β index, a marker of insulin secretion, was similar among groups, suggesting that a short period of lactation, such as the one evaluated in this study, improves insulin resistance, but not insulin secretion." (PMID 37711904, 2023). "In subcutaneous adipocytes harvested from healthy non-pregnant people, testosterone treatment induced insulin resistance in vitro and inhibited insulin-stimulated glucose uptake." (PMID 37766683, 2023). "Previous studies have shown that insulin resistance is an early change that is observed in CKD, and is it worsened by ongoing chronic inflammation, CRTC2 significantly contributes to the development of insulin resistance, and disruption of CRTC2 increases insulin sensitivity." (PMID 37884902, 2023). "Significant differences were observed in baseline variables, including BMI, AFCs, LH levels, LH/FSH ratio, E2 levels, prolactin levels, testosterone levels, homeostasis model assessment of insulin resistance (HOMA-IR) levels and fasting insulin levels (P < 0.05)." (PMID 37388214, 2023). "Accordingly, the present study aimed to evaluate the effect of a specific dose of total polyphenols from poplar propolis on glucose homeostasis and indicators of insulin resistance in non-diabetic insulin-resistant volunteers with obesity." (PMID 37627476, 2023). "The homeostasis model assessment-estimated insulin resistance (HOMA-IR) index is the most common clinical indicator of insulin resistance, but its response to dynamic insulin secretion is limited; thus, we also used the Gutt index and QUICKI, yielding consistent results." (PMID 36688679, 2023).
Insulin resistance (continued). "In addition, mice on the HFHC diet had higher fasting blood glucose levels and insulin secretion than those on the CTL and HFHC + Col diets, with insulin resistance observed as an increase in HOMA-IR compared to the other groups." (PMID 38140293, 2023). "A previous study successfully demonstrated that insulin resistance suppresses LRP1 expression, which may further compromise insulin signaling and cholesterol metabolism in neurons." (PMID 37342358, 2023). "This includes the identification of new kinases and regulated phosphosites that may play a role in insulin-regulated GLUT4 traffic, and clear evidence that GSV-PM interactions are altered in insulin resistance." (PMID 37248992, 2023). "Our results are coherent also with the hypothesis that decreased insulin sensitivity may be a mechanism of altered sleep quality and duration, as highlighted by the increased TDD/Kg (a sign of insulin resistance) in males with poor sleep quality." (PMID 36800003, 2023). "Studies evaluating insulin resistance in TS are less consistent than those evaluating insulin secretion, suggesting that insulin resistance is not the primary driver of hyperglycemia in TS." (PMID 36875465, 2023). "Given the opposite functions of Insulin on hepatic fatty acid oxidation and its influence on PGC-1α signaling, this possibly suggests that KLF14 might have some role to play in insulin resistance." (PMID 36902112, 2023). "It is likely that the higher basal plasma insulin concentrations in Responders than Non-responders compensated for the insulin resistance in Responders, resulting in the same basal metabolite concentrations in both groups." (PMID 37159276, 2023). "Omega-3 lowered fasting blood glucose (FBG) (SUCRAs: 93.53%), and chromium reduced fasting insulin (FINS) (SUCRAs: 72.90%); both were superior to placebo in improving insulin resistance index (HOMA-IR), and chromium was more effective than Omega-3 (SUCRAs: 79.99%)." (PMID 38025704, 2023). "iAsF1-F showed glucose intolerance and insulin resistance with almost no change in blood lipid profiles while iAsF1-M showed improved glucose tolerance and insulin sensitivity with decreased lipid metabolic profiles." (PMID 37691128, 2023). "The obese rats were insulin-resistant and had higher plasma insulin levels and HOMA-IR, but were not diabetic." (PMID 37571269, 2023). "Its circulating levels are increased in obese patients with insulin resistance, and it has a negative correlation with adiponectin levels and insulin sensitivity indices." (PMID 37876013, 2023). "Co‐culture of SIRT2 overexpressing macrophages with aged WT adipose tissue reduced insulin resistance, but the only read out for this is Akt phosphorylation which does not reflect actual insulin action, as mediated by GLUT4 translocation." (PMID 38009412, 2023). "The IR, a highly glycosylated receptor, has 18 glycosylation sites and has implications for insulin resistance, diabetes, and cancer if the insulin-induced IR activation is not functioning correctly." (PMID 36831374, 2023). "Many simplified mathematical models for assessing insulin resistance have been derived in recent years, such as the steady-state model insulin resistance index (HOMA-IR), which is a valid method for assessing insulin resistance calculated from serum glucose and fasting serum insulin." (PMID 37964964, 2023). "Even though in obesity there is insulin resistance in many tissues for various actions of insulin, interestingly, there is no resistance of the effect of insulin on SREPB-1c induction in the liver." (PMID 37545582, 2023). "Insulin resistance is a pathological condition in which cells become nonresponsive to insulin, and the pancreas is signaled to secrete even more insulin to reduce blood sugar." (PMID 36688679, 2023). "The reduced response to insulin stimulation, seen in the cells of the FB of the OBL animals, may recapitulate some of the mechanisms described for insulin resistance in humans." (PMID 37828911, 2023).